RASA1 (RAS p21 protein activator 1)
Description:
GTPase-activating protein (GAP) that stimulates the intrinsic GTPase activity of Ras proteins, such as NRAS, facilitating their transition from the active GTP-bound state to the inactive GDP-bound state, thereby terminating Ras signaling.
Synonyms: GAP; RasGAP; RASA; CM-AVM; p120GAP; p120RASGAP; p120; CMAVM; CMAVM1; PKWS
Tractability: Small molecule: a structure with a bound ligand is known. Antibody: its Gene Ontology location is reachable by antibodies, with medium confidence. PROTAC: its protein half-life has been measured.
Gene: Protein-coding gene on chromosome 5 (87,267,778 to 87,391,939, forward strand). Ensembl gene ENSG00000145715.
Subcellular location: Cytoplasm
Subcellular location (Human Protein Atlas): Basal body; Vesicles; Cytosol
Pathways (Reactome):
Signal Transduction: Downstream signal transduction; PTK6 Regulates RHO GTPases, RAS GTPase and MAP kinases; Regulation of RAS by GAPs; VEGFR2 mediated cell proliferation
Developmental Biology: EPHB-mediated forward signaling
Gene Ontology:
Molecular function: GTPase activator activity; GTPase binding; phosphotyrosine residue binding; protein binding; signaling receptor binding; GTPase activity; potassium channel inhibitor activity; enzyme binding
Biological process: angiogenesis; blood vessel morphogenesis; ephrin receptor signaling pathway; negative regulation of apoptotic process; negative regulation of cell adhesion; negative regulation of cell-matrix adhesion; regulation of actin filament polymerization; signal transduction; intracellular signal transduction; mitotic cytokinesis; negative regulation of neuron apoptotic process; regulation of cell shape; regulation of intracellular signal transduction; regulation of RNA metabolic process; vasculogenesis; system development
Cellular component: cytoplasm; cytosol; plasma membrane; ruffle
Genetic constraint (gnomAD): Loss-of-function variants: 25 observed, 116.53 expected, observed/expected ratio (o/e) 0.21, 90% interval 0.16 to 0.3. The upper end of that interval is the gene's LOEUF score, 0.3, which puts it in group 1 of 6, group 1 being the genes least tolerant of losing a copy. Missense variants: 908 observed, 1,257.9 expected, observed/expected ratio (o/e) 0.72, 90% interval 0.68 to 0.76. Synonymous variants: 449 observed, 447.33 expected, observed/expected ratio (o/e) 1, 90% interval 0.93 to 1.09.
Gene-disease validity (ClinGen):
ClinGen rates the evidence that RASA1 causes each of these diseases.
Noonan syndrome (autosomal dominant): Disputed. Noonan Syndrome (NS) is characterized by short stature, typical facial dysmorphism and congenital heart defects.
Homologues: Orthologues: chimpanzee RASA1 (99% identical), pig RASA1 (97% identical), macaque RASA1 (96% identical), mouse Rasa1 (95% identical), rat Rasa1 (95% identical), dog RASA1 (94% identical), guinea pig RASA1 (92% identical), rabbit RASA1 (90% identical), tropical clawed frog rasa1 (78% identical), zebrafish rasa1a (77% identical), zebrafish rasa1b (72% identical), Drosophila melanogaster vap (42% identical). Paralogues in human: RASAL1 (16% identical), NF1 (15% identical), RASA2 (15% identical), RASA4 (15% identical), RASA4B (15% identical), RASA3 (15% identical), RASAL2 (14% identical), DAB2IP (13% identical), RASAL3 (13% identical).
Diseases named in the same sentence as RASA1 in open-access papers:
RASA1 is named in the same sentence as 118 diseases in open-access papers, as found by Europe PMC text mining. Sharing a sentence is not in itself a finding about the gene and the disease. The quoted sentences say what the papers report.
capillary malformation (32 papers, 2008 to 2026). "Not only germline but also postzygotic mutations in the RASA1 or EPHB4 genes can lead to capillary malformation‐arteriovenous malformation (CM‐AVM) syndrome." (PMID 39498435, 2024). "RASA1 is a GTPase-activating regulator of blood and lymphatic vessel development and is an autosomal dominant cause of capillary malformation–arteriovenous malformation syndrome (CM-AVM) and CCLA in humans." (PMID 38618951, 2024). "Patients with reported mutations in either RASA1 or EPHB4 had family histories of capillary malformation." (PMID 39687400, 2024). "In capillary malformation-AVM with Ephrin type-B receptor 4 (Ephb4) or Ras p21 protein activator 1 (Rasa1) mutation, Col IV accumulates in the EC endoplasmic reticulum, leading to EC apoptotic death." (PMID 38201296, 2024). "A single allele of Ras GAP called Ras p21 protein activator 1 (RASA 1/p120-RasGAP) was sufficient to cause capillary malformation-arteriovenous malformation (CM-AVM)." (PMID 35563380, 2022). "Capillary malformation-arteriovenous malformation (CM-AVM) is a blood vascular anomaly caused by inherited loss-of-function mutations in RASA1 or EPHB4 genes, which encode p120 Ras GTPase-activating protein (p120 RasGAP/RASA1) and Ephrin receptor B4 (EPHB4)." (PMID 35015735, 2022). "The distinct phenotype consisting of multiple small, round-to-oval CMs with surrounding pale halos was associated with germline mutations of RASA-1 and designated capillary malformation-arteriovenous malformation (CM-AVM) in 2003." (PMID 32635943, 2020). "In PWS, the genetic alteration involves the RASA1 gene encoding Ras p21 protein activator 1, involved in capillary malformation–arteriovenous malformation (CM-AVM) syndrome." (PMID 33194904, 2020). "This is in agreement with genetic data that germline mutations of RASA1 in humans cause the capillary malformation-arteriovenous malformation syndrome and other related vascular anomalies, without clear evidence for tumor predisposition." (PMID 31312020, 2019). "RASA1 germline mutations in humans have been linked to capillary malformation-arteriovenous malformation (CM-AVM), an autosomal dominant disorder characterized by atypical capillary malformations." (PMID 26993606, 2016). "CM-AVM is an autosomal dominant disorder caused by heterozygous inactivating mutations in the RASA1 (RAS p21 protein activator 1) gene (CM-AVM1) characterized by the presence of capillary malformations, arteriovenous malformations and fistulas, and occasionally vascular overgrowth." (PMID 33844116, 2021). "Capillary malformation-arteriovenous malformation (CM-AVM) is an autosomal dominant vascular malformation, associated with mutations in the RASA1 gene which have also been identified in capillary malformation (CM), AVM, arterio-venous fistula, and Parkes-Weber syndrome." (PMID 33634164, 2020). "Capillary malformation-arteriovenous malformations (CM-AVMs) caused by a RASA-1 or EPHB4 mutation are characterized as hereditary sporadic or multifocal capillary malformations (CMs), associated with potential fast-flow vascular anomalies underlying erythema lesions." (PMID 32635943, 2020). "Multifocal capillary malformation (CM) is the cardinal feature of patients with RASA1 mutations." (PMID 26132338, 2016). "A total of 37 studies published between 2003 and 2025 were included, encompassing 148 patients diagnosed with capillary malformation–arteriovenous malformation syndrome (CM-AVM) and genetically confirmed to carry either RASA1 or EPHB4 mutations." (PMID 41398316, 2025). "RASA1 is responsible for capillary malformation–arteriovenous malformation syndrome, a phenotype closely related to HHT (OMIM 608354)." (PMID 41300788, 2025). "Capillary malformation‐arteriovenous malformation (CM‐AVM) syndrome, with or without Parkes Weber syndrome, is a rare autosomal dominant disease caused by pathogenic RASA1 or EPHB4 variants." (PMID 39498435, 2024).
capillary malformation (continued). "RASA1 and EPHB4 germ line mutations are generally associated with capillary malformation-arteriovenous malformation syndrome, a disorder that increases the risk of fast-flow malformations and pleural effusion as well as other lymphatic anomalies." (PMID 39687400, 2024). "The placenta-selective gene RASA1 is reported in two diseases characterized by aberrations of blood vessels: the Parkes Weber Syndrome and Capillary Malformation-Arteriovenous Malformation." (PMID 18382664, 2008). "These entities are often sporadic but are found in association with variants of the RASA1 and EPHB4 genes (capillary malformation–arteriovenous malformation, CMAVM; OMIM #608354) or ACVRL1, ENG, and SMAD4 genes (hereditary hemorrhagic telangiectasia, HHT; OMIM #187300)." (PMID 40259928, 2025). "Another well-described syndrome is capillary malformation–arteriovenous malformation (CM-AVM), caused by mutations in RASA1 (RAS p21 protein activator 1) and EPHB4 (Ephrin type-B receptor 4), characterized by multifocal fast-flow lesions and cutaneous vascular malformations." (PMID 41463317, 2025). "According to the test results, cousins (IV:1 and IV:2) have the same variants in ABCG8 (intronic), CTNNA3, and RASA1 genes, involved in the pathogenesis of arrhythmogenic right ventricular cardiomyopathy (CTNNA3) and RASA1 (capillary malformations, Park Weber syndrome)." (PMID 33829027, 2021). "Inactivating mutations in RAS p21 protein activator 1 (RASA1) cause CM-AVM syndrome which is characterized by randomly distributed capillary malformations and predisposition for cerebral and noncerebral AVMs." (PMID 34445743, 2021). "Moreover, isolated port-wine stains are distinct from capillary malformations seen in RASA1 disorders, which will be helpful in clinical evaluation." (PMID 26192947, 2015). "Another genetic disorder involving AVMs is capillary malformation–arteriovenous malformation (CM-AVM) syndrome, which follows an autosomal dominant inheritance pattern due to loss of function variants in RAS P21 Protein Activator 1 (RASA1) and Ephrin Receptor B4 (EPHB4)]." (PMID 40076511, 2025). "Both SNVs have been so far reported just once in gnomAD v.2.1.1 database and they are not included in DECIPHER, the RASA1: c.2656 C > T (p.(Pro886Ser)) is reported in the ClinVar database with uncertain significance in a patient with Capillary malformation-arteriovenous malformation syndrome." (PMID 38874808, 2024).
arteriovenous malformation (24 papers, 2008 to 2026). "Variants in the RASA1 gene are associated with autosomal dominant capillary malformation-arteriovenous malformations (CM-AVM) and Parker Weber syndrome." (PMID 33829027, 2021). "RASA1, a regulator of cardiovascular development, is involved in this pathway and its haploinsufficiency(due to heterozygous mutations) has been identified as the underlying etiology of the autosomal dominant capillarymalformation/arteriovenous malformation (CM/AVM)." (PMID 30507091, 2019). "The etiology of CCT is associated with a mutation of the GNAQ gene, the RASA1 gene, or the MAP2K1 gene.Mutations of the latter two genes are associated with the coexistence of CCT and arteriovenous malformations (AVMs)." (PMID 36013378, 2022). "Mutations in the RASA1 gene (RAS-MAPK pathway) are associated with combined capillary-arteriovenous malformations and Parkes-Weber syndrome, which is characterized by a combination of limb overgrowth with capillary and arteriovenous malformations." (PMID 38790562, 2024). "A similar phenotype has recently been documented in 30 hpf embryos with a loss of Rasa1, a gene linked with arteriovenous malformations, which is not surprising given the known interaction between the Ras and Ephrin signalling pathways." (PMID 38069025, 2023). "In addition to the multiple spots of erythema, fast-flow lesions such as arteriovenous malformation (AVM) or arteriovenous fistula (AVF) as well as hypertrophic syndromes such as Sturge-Weber syndrome (SWS) and Parker-Weber syndrome (PKWS) were also documented in families with a RASA-1 mutation." (PMID 30026675, 2018). "Because RASA1 mutations have previously been associated with capillary and arteriovenous malformations similar to the HHT phenotype, and because no variants were identified in the ENG, ACVRL1, or SMAD4 genes, the RASA1 variant was assumed to be the causative mutation for this sample." (PMID 24268183, 2013).
breast carcinoma (21 papers, 2011 to 2025). "In addition, DOK2 deficiency in ovarian cancer induced carboplatin resistance by inhibiting the apoptosis of tumor cells, while the expression of DOK2/Ras p21 protein activator 1 was associated with prognosis and quality of life of breast cancer patients." (PMID 36268281, 2022). "A former report has discovered that QKI significantly inhibits cell proliferation and arrests cell cycle at G1 phase via the RASA1/MAPK signaling pathway in breast cancer." (PMID 38782769, 2024). "Previous studies demonstrated that miR-21 targets LZTFL1 in breast cancer cells, RASA1 in colon cancer cells, and KLF5 in hepatocellular carcinoma cells." (PMID 37547633, 2023). "The RNA-binding protein QKI can inhibit the progression of breast cancer by regulating the RASA1/MAPK signaling pathway." (PMID 36911413, 2023). "They further determined that miR-132-3p exerts its effects through RASA1, where the delivery of anti-miR-132-3p to vessel endothelium in an orthotopic xenograft mouse model of breast carcinoma restored RASA1 expression and suppressed angiogenesis." (PMID 35456471, 2022). "A number of studies have shown that the dysregulation of RASA1 has an oncogenic effect in multiple types of cancer, including colorectal, liver and breast cancer, as well as promyelocytic leukemia." (PMID 24223656, 2013). "Based on the contrasting expression patterns of miR-31 and RASA1, we proposed that miR-31 was involved in the pathogenesis of ICC by directly inhibiting the protein expression of RASA1, a validated oncogene in colorectal, liver and breast cancer, as well as promyelocytic leukemia." (PMID 24223656, 2013). "RASA1 has been reported to be a CNA in breast cancers and a putative tumor suppressor gene." (PMID 21339820, 2011). "Moreover, the downregulation of the RAS-GAP RASA1 in a large percentage of breast cancer cases and a small percentage of cases with KRAS mutations suggests that RAS hyperactivity commonly drives breast cancer cases overall." (PMID 38540084, 2024). "In addition, miR-133a targeting of EGFR, miR-200c and miR-30c targeting of KRAS, miR-148b targeting of NRAS, miR-7 targeting of RAF1, miR-206 targeting of RASA1 and miR-21 targeting of SPRED1 have been reported in breast cancer cells." (PMID 27462780, 2016). "Moreover, the combined negative expression of DOK2 and RASA1 may function as an independent prognostic factor for patients after breast cancer surgery." (PMID 40668798, 2025). "miR-335 appears to control growth by blocking cell proliferation by targeting certain genes; e.g., RASA1 in rat epididymal development, SP1 and Bcl-w in non-small cell lung cancer, SOX4 and TNC in breast cancer, ROCK1, MAPK1, and LRG1 in neuroblastoma, and Rb1 in U2OS osteosarcoma cells." (PMID 26204513, 2015).
colorectal cancer (21 papers, 2014 to 2025). A primary or metastatic malignant neoplasm that affects the colon or rectum. "It has also been found in colorectal cancer that RASA1 mutation or loss of function leads to activation of the RAS-MAPK cascade." (PMID 31857500, 2019). "miR-31 targets human mutL homolog 1 (a mismatch repair protein) and activates the RAS pathway by inhibiting RAS p21 GTPase activating protein 1 (RASA1) in colorectal cancer." (PMID 28239461, 2017). "In colorectal cancer, it was demonstrated that miR-31 plays a significant role in activating the RAS signaling pathway through the inhibition of RASA1 translation, thereby improving colorectal cancer cell growth and stimulating tumorigenesis." (PMID 25797269, 2015). "The activation of anti-apoptotic and pro-survival cascades by miR-31 has also been reported in colorectal cancer via the repression of RASA1, a suppressor of RAS oncogene." (PMID 25068518, 2014). "MiR-21, a well-known pro-inflammatory microRNA associated with colorectal cancer, inhibits the expression of RAS-GTPase activating protein family member RASA1, resulting in the sustained activation of the RAS signaling pathway and the subsequent initiation and progression of colorectal cancer." (PMID 39360320, 2024). "RASA1, acting as the suppressor of RAS functions, is involved in the tumorigenicity of colorectal cancer and gastric cancer." (PMID 26126858, 2015). "For example, in colorectal cancers, the overexpression of miR-31 was implied to accelerate tumor proliferation through activating the RAS pathway and regulate the expression of RAS p21 GTPase activating protein 1 (RASA1) at a posttranscriptional level." (PMID 36844871, 2023). "Thus, Fusobacterium nucleatum–induced proliferation of colorectal cancer cells and tumor development activate TLR4 and RASA1 signaling." (PMID 32422978, 2020). "Besides the APC gene, which occurs in over two-thirds of colorectal cancer, WNT2 and MACF1 also impact the Wnt pathway, while RASA1 is in the RAS pathway." (PMID 25974029, 2015).
Parkes Weber syndrome (20 papers, 2008 to 2025). "Parkes-Weber syndrome (PKWS) is caused by pathogenic variants in the RAS p21 protein activator 1 (RASA1), a Ras-GTPase activating protein." (PMID 38894719, 2024). "The clinical features raised the suspicion of CM-AVM syndrome presenting with a Parkes Weber syndrome-like phenotype, which was molecularly confirmed by the presence of the heterozygous variant NM_002890.2:c.768C>A in the RASA1 gene." (PMID 36980822, 2023). "In 2020, a case of Parkes Weber syndrome associated with RASA1 mosaic mutation was reported." (PMID 39918133, 2025). "In addition, a novel sporadic case of Parkes Weber syndrome (PWS) due to an RASA1 mosaic pathogenic variant was described." (PMID 35740480, 2022). "The search for the causal gene mutation can be carried out (mutations of the RASA1 and EPHB4 genes, identified respectively in CM-AVM type 1, which includes Parkes-Weber syndrome, and CM-AVM type 2)." (PMID 39885577, 2025). "Cutaneous vascular lesions are a common hallmark of developmental vascular disorders such as RASA1- and EPHB4-mutated CM-AVM25,27, ENG1- and ACVRL1-mutated HHT29, and RASA1-mutated Parkes Weber syndrome, among others." (PMID 37978175, 2023). "RASA1 mutations have been demonstrated in familial AVM, SWS, KTS and Parkes-Weber syndrome, suggesting that germline mutations in RASA1 are associated with familial susceptibility to these VAs." (PMID 33634164, 2020). "Notably, recent studies have identified mutations in RASA1 and EPHB4 in CM-AVM and Parkes Weber syndrome, respectively, highlighting the potential utility of genetic testing in complex cases." (PMID 40357088, 2025). "We here present a Parkes Weber syndrome patient with a negative family history and a mosaic RASA1 loss‐of‐function mutation detected with a variant allele frequency of 20% in her blood and oral epithelial cells." (PMID 39498435, 2024).